TFAM (transcription factor A, mitochondrial)
Diseases named in the same sentence as TFAM in open-access papers (continued):
Sharing a sentence is not in itself a finding about the gene and the disease.
cancer (continued). "Upon activation by norepinephrine, ATF1 potentiates cancer stemness by coordinated trans-activation of both nuclear pluripotency factors MYC/NANOG and mitochondrial biogenesis regulators NRF1/TFAM, thereby orchestrating nuclear reprograming and mitochondrial rejuvenating." (PMID 37463926, 2023). "Next, we knocked down the TFAM expression to decrease the mtDNA copy number and to achieve mitochondrial respiratory dysfunction in a GAC cell line and then evaluated the consequence on cancer glucose metabolism and the aggressiveness of cancer cells." (PMID 35163779, 2022). "Localisation of SIRT1 to the mitochondria following exercise may also occur, with one study in a human carcinoma cell line finding SIRT1 co-localised with PGC-1α and TFAM in the inner matrix." (PMID 35163441, 2022). "One study in human carcinoma cells reported PGC-1α to localise with mitochondrial transcription factor A (TFAM), a non-sequence specific transcription factor required for mtDNA expression and replication." (PMID 35163441, 2022). "The molecular mechanisms behind glycolysis arrest induced by TFAM have not been elucidated in cancer cells." (PMID 31600993, 2019). "Therefore, in this research, we aimed at exploring the interconnections between TFAM and COX-2 in irradiated cancer cells." (PMID 30862036, 2019). "Both TFAM and COX-2 contribute to the resistance of cancer cells to radiation, and they are considered as potential targets for improving the efficacy of radiation treatment in cancers." (PMID 30862036, 2019). "We hypothesized that melatonin can reduce the expression of mitochondrial transcription factors (TFAM, TFMB1M, and TFB2M) to decrease the viability of cancer cells due to an imbalance in mitochondrial activity." (PMID 29747444, 2018). "TFAM depletion-induced changes in cell morphology have not previously been reported, whereas those in proliferation inhibition have been reported in some cancer cells." (PMID 29259235, 2017). "However, although TFAM expression has been involved in the etiology of several different types of cancer, until now, there is no direct evidence of a TFAM-post-translational modification role in carcinogenesis." (PMID 41602822, 2026). "However, there is no direct evidence showing that TFAM modifications are correlated with cancer." (PMID 32039210, 2020). "Interestingly, TFAM depletion was found to decrease the rate of cell division as cells organize into polarized growth-arrested polygonal shaped colonies, which is a common phenotype observed in non-malignant cancer cells." (PMID 29259235, 2017). "However, the roles of TFAM have not been fully identified in cancer cells." (PMID 24137381, 2013). "Although we did not evaluate the protein levels of TFAM in GAC patients’ specimens in this study, relevant results have been reported in other human cancers." (PMID 35163779, 2022).
infection (24 papers, 2016 to 2026). The state of being infected such as from the introduction of a foreign agent such as serum, vaccine, antigenic substance or organism. "The stability ranking at different developmental stages associated with infection of PWN was as the following: TER > RPL7 > RPS5 > Zdhhc15 > EF1-γ > RPL18 > Tmub1 > SNX6 > ATPase > TFAM > α-TUB > EIF > TPI > COX7." (PMID 35547586, 2022). "Because infection induced the expression of TFAM and TWNK, we posited that ATF4 regulated mtDNA levels in a TFAM- and TWNK-dependent manner." (PMID 40811546, 2025). "We posited that the increase in mtDNA was regulated by an infection-induced transcription factor upstream of TFAM and TWNK." (PMID 40811546, 2025). "Immunohistochemistry performed three days post-infection shows a significant increase in nuclear levels of the transcription factor TFAM in astrocytes expressing tau 4R (V5+)." (PMID 40122883, 2025). "Finally, to explore the relationship between TFAM and Nrf2 and the effect of TFAM on mitochondrial morphological function, lentiviral infection was used to construct a stable HaCaT cell line with low expression of the TFAM gene." (PMID 39794424, 2025). "Taken together, the observed downregulation of PACK and TFAM in P. undulata-supplemented tilapia suggests a coordinated metabolic adaptation aimed at optimizing resource allocation for immune defense and minimizing infection-induced stress." (PMID 40404688, 2025). "Other transcriptional genetic control of AMs includes mitochondrial transcription factor A (TFAM), whereby its deficiency results in impaired OXPHOS, leading to reduced numbers of mature AM, accumulated surfactants, and increased susceptibility to infection." (PMID 37822933, 2023). "In addition, the anti-dsDNA antibody coimmunoprecipitated with cGAS, DDX41, and TFAM in cGAS-293FT cells after infection with WT PR8 influenza virus." (PMID 31604929, 2019). "A further novel finding concerns VacA-independent mitochondrial deregulation, observed in H. pylori 26695∆vacA-infected cells, where TOM22, TIM23, POLG and TFAM were induced shortly upon infection, although at a lower extent and delayed compared to 26695 infection." (PMID 29162845, 2017). "Importantly, mutations in the mitochondrial replisome’s proteins POLG, TFAM, and MGME1 genes are associated with the accumulation of mtDNA deletions that may also increase susceptibility for infection-induced chronic-inflammation-associated disease." (PMID 39906209, 2024). "In view of the fact that ROS affect various transcription factors such as nuclear factor kappa-light-chain-enhancer of activated B cells (NF-κB) and activator protein-1 (AP-1), we identify whether DPI treatment affected the NRF1/2/TFAM signaling at 16 h after infection." (PMID 31011285, 2019). "Therefore, the late POLG and TFAM up-regulation in vivo could likely be VacA-independent, as observed at late infection time-points in vitro." (PMID 29162845, 2017). "Two multiplicities of infection (MOIs) were tested, and, for each cell line, the MOI that yielded the greatest increase in TFAM mRNA expression and mtDNA copy number was selected." (PMID 41226485, 2025). "Metformin treatment significantly increased protein expression levels of PGC-1α and TFAM compared to controls, and attenuated MAC-mediated decreases during a 24-hour infection period as determined by densiometric evaluation of Western Blot bands." (PMID 39913377, 2025). "Metformin treatment significantly increased protein expression levels of PGC-1α and TFAM compared to controls, and blunted MAC-mediated decreases during a 6-hour infection period, as determined by densiometric evaluation of Western Blot bands." (PMID 39913377, 2025). "Of note, the protein interaction between TFAM and TFB2M is just one promising example among many significant protein interactions involved in severe infections like critical COVID-19." (PMID 40458415, 2025).
infection (continued). "ZLN005 treatment significantly increased protein expression levels of PGC-1α and TFAM compared to controls, and attenuated MAC-mediated decreases during a 24-hour infection period as determined by densiometric evaluation of Western Blot bands." (PMID 39913377, 2025). "A similar trend was observed in TFAM mRNA (tfam), with ZLN005 treatment significantly increasing expression compared to controls and attenuating MAC-mediated decreases during 6-hour infection and 24-hour infection." (PMID 39913377, 2025). "ZLN005 treatment significantly increased protein expression levels of PGC-1α and TFAM compared to controls, and blunted MAC-mediated decreases during a 6-hour infection period, as determined by densiometric evaluation of Western Blot bands." (PMID 39913377, 2025). "Of pathophysiological relevance, infection with Herpes simplex virus‐1 (HSV‐1) or vesicular stomatitis virus (VSV) results in mtDNA stress, TFAM depletion and mtDNA entrance into the cytoplasm." (PMID 32202065, 2020). "In primary human bronchial epithelial cells, 100 μM 3-oxo-C12-HSL and infection with PAO1 similarly reduced expression of PGC-1α and TFAM." (PMID 31417101, 2019). "Contrary to our expectation, the loss of ATF4 did not block the increase in TFAM and TWNK transcripts during infection." (PMID 40811546, 2025). "At the early stage of infection, H. pylori induce VacA dependent dysregulation of mitochondria hemostasis, which promotes transient increase in mitochondrial translocases, mitochondrial DNA replication maintenance factors such as POLG and TFAM." (PMID 39906209, 2024). "Infection with the PAO1 strain in BEAS-2B bronchial epithelial cells decreases the expression of PGC-1α, mitochondrial transcription factor A (TFAM), the mitochondrial-localized NAD+ deacylase sirtuin 3 (SIRT3), and nuclear factor erythroid 2-related factor 2 (NRF2)." (PMID 35215060, 2022). "First, early upon infection VacA induces transient increase of mitochondrial translocases and a dramatic accumulation of the mitochondrial DNA replication and maintenance factors POLG and TFAM." (PMID 29162845, 2017). "In addition, we found that infection with EMCV but not influenza virus or adenovirus reduced the expression levels of TFAM." (PMID 31604929, 2019). "However, the PGC-1α and TFAM expression levels were not altered by MeV infection, as determined by RT-qPCR, and were not included in the list of downregulated genes post-infection for all of these viruses." (PMID 34648591, 2021). "Upon infection with either strains, most (≥71.3%) TFAM appeared localized in mitochondria (TFAM+/TOM22+), although in the absence of VacA, TFAM appeared concentrated in a few mitochondria (19.0 ± 1.4% of signal) at 2 h pi." (PMID 29162845, 2017). "Thus, early upon infection and in the absence of VacA, only a small fraction of mitochondria was enriched in POLG and TFAM, despite extramitochondrial POLG and to a minor extent TFAM were observed with either H. pylori strains." (PMID 29162845, 2017).
neurodegenerative disease (18 papers, 2017 to 2025). A disorder of the central nervous system characterized by gradual and progressive loss of neural tissue and neurologic function. "TFAM protein levels in the CNS were shown to be reduced by ~43% in some AD, PD, and HD patients, demonstrating the association of TFAM abnormalities with a variety of neurodegenerative diseases." (PMID 36157077, 2022). "In recent works, the overexpression of TFAM increased the mtDNA copy count, promoted mitochondrial function, and improved the neurological dysfunction of neurodegenerative diseases." (PMID 38333750, 2024). "Mitochondria-derived DAMPs (mtDAMPs) such as cell-free mitochondrial DNA (mtDNA), mitochondrial transcription factor A (TFAM), and cardiolipin have been linked to chronic inflammation in aging and degenerative diseases that activate an immune response." (PMID 40757564, 2023). "Given the implication of TFAM in neurodegenerative diseases such as PD, we next analyzed the regulation of this gene by C/EBPβ." (PMID 36674978, 2023). "The role of TFAM in neurodegenerative diseases has been well explained." (PMID 38333750, 2024). "Emerging evidence indicates that altered TFAM levels or mtDNA copy numbers may impact mitochondrial homeostasis in Alzheimer's and other neurodegenerative diseases." (PMID 37715225, 2023). "The proinflammatory activity of extracellular TFAM demonstrated in peripheral tissues suggests that it could also play a role in the CNS inflammation observed in neurodegenerative diseases." (PMID 31065234, 2019). "Most likely, the quantitative disorder and functional impairments in TFAM and PGC-1α may affect mitochondrial homeostasis in neurodegenerative diseases." (PMID 32054039, 2020). "The mitochondrial transcription factor A (TFAM) essential for genome maintenance, creatine kinase U-type (CKMT1) involved in energy metabolism, and mitochondrial fission factor (MFF) involved in the mitochondrial fission process are often decreased in neurodegenerative diseases including AD." (PMID 35269905, 2022).
mitochondrial disease (10 papers, 2016 to 2026). "Because its function is tightly associated with mtDNA, TFAM has a protective role in mitochondrial diseases, and supportive studies demonstrate reversal of disease phenotypes by TFAM overexpression." (PMID 41649246, 2026). "A study that claims to be the first to describe a pathology caused by changes in TFAM function showed its correlation with mitochondrial diseases." (PMID 32649732, 2020). "While the global knockout of TFAM in embryonic development proves lethal, the targeted disruption thereof within tissues replicates mitochondrial disease manifestations found across various patient populations." (PMID 38247538, 2024). "The modulation of mtDNA copy number by manipulating TFAM levels may provide a future route to treat not only primary mitochondrial diseases but also to intervene in other human pathologies characterized by mitochondrial impairment." (PMID 35054416, 2021). "Conversely, high TFAM expression in transgenic mice increased the number of mtDNA copies, showing that this increase may improve severe symptoms of certain mitochondrial diseases." (PMID 30845180, 2019). "Whole deletion of TFAM is embryonically lethal, but tissue-specific lack of TFAM disrupts respiratory chain function and generates a variety of alterations that recapitulate important phenotypes of human mitochondrial diseases." (PMID 36474281, 2022). "Tissue-specific absence of TFAM impairs OXPHOS, leads to genetic mitochondrial diseases in both humans and mice 40-41." (PMID 41424862, 2026).
metabolic disease (9 papers, 2020 to 2025). A congenital disorder (due to inherited enzyme abnormality) or acquired (due to failure of a metabolically important organ) disorder resulting from an abnormal metabolic process. "TFAM dysregulation has been associated with aging, metabolic disorders, and neurodegenerative diseases, underscoring its critical role in maintaining mt homeostasis and its potential as a therapeutic target for mitigating mt dysfunction." (PMID 40418056, 2025). "Some studies have demonstrated that senescence is associated with mitochondria in T cells, damaged mitochondria induced by deficiency of mitochondrial transcription factor A (TFAM) works as the accelerator of senescence which causes T cells metabolic disorder and then leads to chronic inflammation." (PMID 36212470, 2022). "Dysregulation of TFAM leads to mtDNA instability, impaired ETC function, and increased susceptibility to oxidative stress‐related diseases such as neurodegeneration and metabolic disorders." (PMID 40418056, 2025). "Numerous studies report a correlation between DNA methylation of the PGC-1α and TFAM promoter regions and their subsequent transcription with the mtDNA copy number in metabolic disease condition." (PMID 36247432, 2022). "TFAM is a mitochondria specific transcription factor involved in replication of mitochondrial genome and in maintenance of mtDNA copy number, whereas Drp1 regulates mitochondrial fission and is a potential therapeutic target in metabolic diseases." (PMID 31514051, 2020).
neurological diseases (4 papers, 2019 to 2024). "The GO biological process mostly enriched by the up-regulated genes was nervous development, which might be related to TFAM function in neurological diseases." (PMID 34876009, 2021). "Hence, these studies show that mitochondrial biogenesis, or more specifically TFAM, may be a therapeutic target for ART and HIV-induced neurological disorders." (PMID 31748578, 2019).
cardiovascular disease (3 papers, 2021 to 2023). "In peripheral blood T cells, impaired TFAM expression causes premature senescence and multimorbidity (including metabolic, cognitive and cardiovascular disorders)." (PMID 37679776, 2023).
kidney (3 papers, 2023 to 2025). "In addition, miR-709 targets TFAM (mitochondrialtranscriptional factorA), a key factor in mitochondrial function.Inhibiting miR-709 reduces kidney injury and dysfunction in mice.These findings suggest that miR-709 is a potential target for AKItreatment." (PMID 39365293, 2024).
cardiac diseases (2 papers, 2019 to 2021). "Furthermore, nuclear gene mutations, regulating mtDNA replication and maintenance, such as mitochondrial transcription factor A (TFAM), mtDNA polymerase γ (POLG), and PEO1 (Twinkle) genes have been associated with cardiac diseases." (PMID 34072184, 2021).
endocrine disorders (1 paper, 2021). "Recently, it was proposed that the reduced expression of both mitochondrial transcription factors TFAM might be associated with different endocrine disorders." (PMID 34732209, 2021).
myopathy (1 paper, 2022). A disease of the muscle in which the muscle fibers do not function properly. "In muscle-specific TFAM knockout mice, used to model myopathy, increased mitochondrial copy numbers were found as potential compensation mechanism for the reduced function of the ETC." (PMID 35216315, 2022). "Next, we compared the expression of selected mtDNA-encoded genes (CYTB, COX1, ND1, and ND6) and nuclear-encoded genes involved in mitochondrial biogenesis (PPARGC1A and transcription factor A (TFAM)) in skin fibroblasts from healthy controls versus those from myopathy patients." (PMID 35216315, 2022).
peripheral neuropathy (1 paper, 2021). A disorder affecting the peripheral nervous system. "It is suggested that TFAM activation may be a therapeutic strategy for treating peripheral neuropathy." (PMID 34572446, 2021).
TFAM also shares sentences with these, for which no sentence is quoted: Parkinsonism (10 papers); ischemic stroke (4); Anxiety (2); aortic aneurysm (2); chronic obstructive pulmonary disease (2); diabetic neuropathy (2); infertile (2); influenza (2); intestinal cancer (2); lipodystrophy (2); lymph node metastases (2); metabolic syndrome (2); nonalcoholic steatohepatitis (2); Perrault syndrome (2); renal carcinoma (2); squamous cell lung carcinoma (2); Ureteral obstruction (2); adenocarcinoma (1); alcohol (1); alcoholic hepatitis (1); alcoholic steatohepatitis (1); amnesia (1); amyotrophic lateral sclerosis (1); arteriovenous malformations (1); AV block (1); B cell lymphoma (1); bacterial gastritis (1); bacterial infections (1); brain cancer (1); Burkitt lymphoma (1).
A further 51 diseases each share a sentence with TFAM in 1 paper.